PNOC (prepronociceptin)
Description:
[Nociceptin]: Ligand of the opioid receptor-like receptor OPRL1. It may act as a transmitter in the brain by modulating nociceptive and locomotor behavior. May be involved in neuronal differentiation and development. [Nocistatin]: Blocks nociceptin action in pain transmission by inhibiting nociceptin-induced hyperalgesia and allodynia. [Orphanin FQ2]: Has potent analgesic activity.
Synonyms: OFQ; PPNOC; N/OFQ; NOP; ppN/OFQ
Tractability: Antibody: its Gene Ontology location is reachable by antibodies, with high confidence; UniProt places it where antibodies can reach, with medium confidence; UniProt predicts a signal peptide or a membrane-spanning region.
Safety:
Unwanted effects reported when the protein is acted on. In parentheses: how it was acted on, where the effect was seen, and who reports it.
require treatment with at least two medications for neonatal abstinence syndrome (source: ClinPGx)
Gene: Protein-coding gene on chromosome 8 (28,316,986 to 28,343,355, forward strand). Ensembl gene ENSG00000168081.
Subcellular location: Secreted
Subcellular location (Human Protein Atlas): Vesicles; Predicted to be secreted
Pathways (Reactome):
Signal Transduction: G alpha (i) signalling events; Peptide ligand-binding receptors
Gene Ontology:
Molecular function: neuropeptide hormone activity; opioid peptide activity; opioid receptor binding; receptor ligand activity
Biological process: neuron-neuron synaptic transmission; neuropeptide signaling pathway; sensory perception; sensory perception of pain; signal transduction; behavioral response to ethanol; cellular response to ethanol; chemical synaptic transmission; drinking behavior; female pregnancy; gamma-aminobutyric acid secretion, neurotransmission; locomotion involved in locomotory behavior; modulation of excitatory postsynaptic potential; modulation of inhibitory postsynaptic potential; multicellular organismal response to stress; regulation of dopamine secretion; regulation of synaptic transmission, GABAergic; regulation of synaptic transmission, glutamatergic; response to cocaine; response to ethanol; response to morphine; response to nicotine
Cellular component: extracellular region; neuronal cell body; synaptic membrane; presynapse
Genetic constraint (gnomAD): Loss-of-function variants: 10 observed, 15.32 expected, observed/expected ratio (o/e) 0.65, 90% interval 0.4 to 1.11. The upper end of that interval is the gene's LOEUF score, 1.11, which puts it in group 4 of 6, group 1 being the genes least tolerant of losing a copy. Missense variants: 220 observed, 230.14 expected, observed/expected ratio (o/e) 0.96, 90% interval 0.86 to 1.07. Synonymous variants: 98 observed, 91.61 expected, observed/expected ratio (o/e) 1.07, 90% interval 0.91 to 1.26.
Homologues: Orthologues: chimpanzee PNOC (100% identical), macaque PNOC (97% identical), rabbit PNOC (88% identical), dog PNOC (86% identical), pig PNOC (85% identical), guinea pig PNOC (83% identical), mouse Pnoc (81% identical), rat Pnoc (78% identical), zebrafish pnocb (36% identical), zebrafish pnoca (36% identical), tropical clawed frog pnoc (35% identical). Paralogues in human: PENK (23% identical), PDYN (19% identical).
Diseases named in the same sentence as PNOC in open-access papers:
PNOC is named in the same sentence as 34 diseases in open-access papers, as found by Europe PMC text mining. Sharing a sentence is not in itself a finding about the gene and the disease. The quoted sentences say what the papers report.
Obesity (3 papers, 2018 to 2025). Accumulation of substantial excess body fat. "Findings include missense variants in established drug targets for sleep disorders (HCRTR1, HCRTR2), genes with roles in arousal (TRPC6, PNOC), and genes suggesting an obesity-hypersomnolence pathway (PNOC, PATJ)." (PMID 33568662, 2021). "To investigate the expression of PNOC mRNA in human adipose tissue, we conducted an analysis using an RNA sequencing dataset that includes 1,480 visceral adipose tissue samples obtained from the Leipzig Obesity BioBank (LOBB)." (PMID 40662198, 2025). "We identify 123 loci of which 61 replicate in the 23andMe research cohort, including variants in established drug targets for sleep disorders (HCRTR1, HCRTR2), genes with roles in arousal (TRPC6, PNOC), and genes suggesting an obesity-hypersomnolence pathway (PNOC, PATJ)." (PMID 33568662, 2021).
breast carcinoma (2 papers, 2021 to 2026). "Furthermore, a previous study found that a risk model composed of PTGDR, PNOC and CCL23 was helpful in predicting the prognosis of HER2-positive breast cancer, and that patients with low risk scores may benefit from immunotherapy." (PMID 41383978, 2026). "In our study, PNOC expression was higher in breast cancer samples of nonobese patients than of obese patients." (PMID 34566889, 2021).
cholangiocarcinoma (2 papers, 2021 to 2025). A carcinoma that arises from the intrahepatic biliary tree (intrahepatic cholangiocarcinoma) or from the junction, or adjacent to the junction, of the right and left hepatic ducts (hilar cholangiocarcinoma). "Notably, PNOC expression in B cells has been previously identified within the tumor microenvironment of cholangiocarcinoma, where it is associated with increased immune infiltration and positively correlated with improved patient survival outcomes." (PMID 40662198, 2025). "In our analysis, PNOC was up-regulated in cholangiocarcinoma samples, though the difference didn’t achieve significance." (PMID 33841428, 2021). "These functionally different cell populations in tumor justify the need of combining immune therapy in cholangiocarcinoma, and PNOC and LAIR2 could be clinical biomarkers for patient evaluation before immune therapy, predicting patients’ survival and tumor immune infiltration accordingly." (PMID 33841428, 2021). "There were 43 genes differentially expressed between high- and low-immune infiltrated patients, and after further compression, PNOC and LAIR2 were significantly correlated with high immune infiltration status in cholangiocarcinoma." (PMID 33841428, 2021). "PNOC and LAIR2 were biomarkers for immune infiltration evaluation in cholangiocarcinoma." (PMID 33841428, 2021).
glioma (2 papers, 2021 to 2022). A benign or malignant brain and spinal cord tumor that arises from glial cells (astrocytes, oligodendrocytes, ependymal cells). "In cancer research, PNOC is highly expressed in glioma cells, epithelial ovarian cancer, and other tumors and has been reported as a prognostic biomarker." (PMID 35432443, 2022). "PNOC expression was found to be significantly upregulated in gliomas." (PMID 34566889, 2021).
brain tumors (1 paper, 2021). "Moreover, the overexpression expression of PNOC has been identified in other brain tumors." (PMID 33345275, 2021).
cardiac hypertrophy (1 paper, 2022). "More research is needed to elucidate if the distinct upregulation of PNOC forms part of any cardioprotective mechanisms or if it may play a role in the long-term progression of cardiac hypertrophy." (PMID 35207580, 2022).
complex regional pain syndrome (1 paper, 2019). A chronic pain syndrome characterized by a disproportionate spontaneous or stimulus-induced pain, accompanied by a variably mixed myriad of autonomic and motor disorders including symptoms such as swelling, allodynia, skin blood supply and trophic disturbances. "There is a network centered on GNG7, that may be involved in connectivity/signaling, comprising HTR2A, EDN1, PNOC (involved in pain signaling) and CALCA (involved in Reflex Sympathetic Dystrophy and Complex Regional Pain Syndrome)." (PMID 30755720, 2019).
gastric cancer (1 paper, 2022). A primary or metastatic malignant neoplasm involving the stomach. "The results of immunohistochemistry showed that the protein expression levels of RBP7, DES, SPP1, VIP, and PRKCG in gastric cancer tissues were higher than those in normal tissues, while PNOC, TNFRSF12A, and TUBB3 proteins are less expressed in gastric cancer tissues than normal tissues." (PMID 35174205, 2022).
ovarian carcinoma (1 paper, 2018). A malignant neoplasm originating from the surface ovarian epithelium. "Examination of the resulting network shows that RPS19, PNOC, SFRP1 and KCNJ16 are connected to other frequently altered genes, including MYC or EIF3E as oncogenes, from TCGA ovarian cancer dataset." (PMID 30255801, 2018).
psoriasis (1 paper, 2021). An autoimmune condition characterized by red, well-delineated plaques with silvery scales that are usually on the extensor surfaces and scalp. "In psoriasis uninvolved skin, positive correlations were found between the expression levels of CREB1 and LEF1 (r = 0.66, p < 0.05), USF1 and PNOC (r = 0.81, p < 0.05), MITF and ATRN (r = 0.58, p < 0.05), MITF and NURR1 (r = 0.56, p < 0.05) and MITF and MAPK14 (r = 0.75, p < 0.01)." (PMID 34884858, 2021).
schizophrenia (1 paper, 2015). A major psychotic disorder characterized by abnormalities in the perception or expression of reality. "The marginally preserved turquoise module had 13 and 16 hub genes in CTS and SZP, respectively, with an overlap of only eight hubs, from which three were previously associated with schizophrenia: ADARB1, PNOC and XK." (PMID 25981335, 2015).
substance abuse (1 paper, 2021). The use of a drug for a reason other than which it was intended or in a manner or in quantities other than directed. "Some of us previously investigated involvement of eight genes in the opioid system (OPRD1, OPRK1, OPRL1, OPRM1, PDYN, PENK, PNOC, and POMC) and their potential effects on substance abuse." (PMID 34440333, 2021).
vitiligo (1 paper, 2021). Generalized well circumscribed patches of leukoderma that are generally distributed over symmetric body locations and is due to autoimmune destruction of melanocytes. "With regard to inflammatory skin disorders, we have previously reported altered expression of PNOC and its receptor in vitiligo." (PMID 34884858, 2021). "Previously, our research group has reported an increase in the mRNA expression of PNOC and its receptor ORPL1 in vitiligo involved skin compared to healthy controls." (PMID 34884858, 2021).
tumor (6 papers, 2021 to 2025). "We observed that PNOC expression strongly correlated with more robust anti-tumor immune responses, characterized by enhanced CD8+ T-cells and B-cells infiltration, as well as decreased levels of immunosuppressive subsets such as myeloid-derived suppressor cells (MDSCs) (SF." (PMID 40951290, 2025). "Additionally, from 8 reported markers reflecting B-cell level in tumor environment, some of them, such as PNOC, FCRL2, CD19, were found to have different degrees of impact on poorer prognosis on overall survival of ccRCC cohort." (PMID 37908350, 2023). "2A–D) single-cell RNA-seq datasets showed that PNOC is predominantly expressed by tumor-infiltrating B-cells, with little to no expression in other immune or tumor cells." (PMID 40951290, 2025). "The expressions of CCR1, PNOC, and VIP genes were significantly correlated with tumor purity, B cell infiltration, CD8+T cell infiltration, CD4+T cell infiltration, macrophage infiltration, neutrophil infiltration and dendritic cell infiltration, and the differences were statistically significant." (PMID 35174205, 2022). "We found PNOC was highly expressed in tumors, though the difference between normal and tumor tissues was not significant." (PMID 33841428, 2021).
cancer (4 papers, 2013 to 2023). A tumor composed of atypical neoplastic, often pleomorphic cells that invade other tissues. "In contrast, PNoc expression was reduced in cancer and septic patients but not in postoperative patients." (PMID 24066107, 2013).
PNOC also shares sentences with these, for which no sentence is quoted: Anxiety (6 papers); depression (2); Sepsis (2); airway hyperresponsiveness (1); alcohol dependence (1); alexithymia (1); dementia (1); diabetic neuropathy (1); Headache (1); inflammatory bowel disease (1); laryngeal carcinoma (1); lymph node metastasis (1); melanoma (1); migraine (1); periodontitis (1); post-traumatic stress disorder (1); psychiatric disorder (1); rheumatoid arthritis (1); sleep disorder (1).